SPDEF (SAM pointed domain containing ETS transcription factor)
Diseases named in the same sentence as SPDEF in open-access papers (continued):
Sharing a sentence is not in itself a finding about the gene and the disease.
glioma (1 paper, 2021). A benign or malignant brain and spinal cord tumor that arises from glial cells (astrocytes, oligodendrocytes, ependymal cells). "This study looked at the differential expression of lncRNA in glioma cells as well as the effect of LncRNA NKX3-1 on glioma cells via SPDEF-related pathways." (PMID 34350121, 2021). "So this study investigates the effect of NKX3-1 on the proliferation, invasion, and migration of glioma cells, as well as the relationship between SPDEF-related pathways." (PMID 34350121, 2021). "We investigated the differential expression profile of lncRNAs in glioma and discovered that the lncRNA NKX3-1 plays an important role in cancer promotion via the Fem1b/SPDEF pathway." (PMID 34350121, 2021). "SPDEF was discovered to interact with NKX3-1 and androgen receptor in prostate epithelial cells, regulating the expression of prostate-specific antigen (PSA), but little is known about NKX3-1 through SPDEF-related pathways in glioma." (PMID 34350121, 2021).
head and neck squamous cell carcinoma (1 paper, 2021). A squamous cell carcinoma that arises from any of the following anatomic sites: lip and oral cavity, nasal cavity, paranasal sinuses, pharynx, larynx, and salivary glands. "However, the biological role of SPDEF in head and neck squamous cell carcinoma (HNSCC) remains unclear." (PMID 34667150, 2021).
lung adenocarcinoma (1 paper, 2017). A carcinoma that arises from the lung and is characterized by the presence of malignant glandular epithelial cells. "The prognostic values of TOX3 and SPDEF expression in lung adenocarcinoma were shown as forest plots, which were derived from the PrognoScan database with a Cox p-value < 0.05, and the Kaplan–Meier plotter database with a log-rank p-value < 0.05." (PMID 29285217, 2017). "The results showed that both TOX3 and SPDEF are significantly upregulated in lung adenocarcinoma, compared to normal tissue." (PMID 29285217, 2017). "The results showed that the mRNA expression of either TOX3 or SPDEF is upregulated in lung adenocarcinoma." (PMID 29285217, 2017). "Our study suggests that SPDEF may play an oncogenic role in lung adenocarcinoma, although some reports have shown that SPDEF can suppress cancer metastasis." (PMID 29285217, 2017). "The analysis of the effects from each gene expression on survival outcome indicated that 6 genes (AGR2, SPDEF, CDKN2A, CLDN3, SFN, and PHLDA2) play oncogenic roles, and 7 genes (PDK4, FMO2, CPED1, GNG11, IL33, BTNL9, and FABP4) act as tumor suppressors in lung adenocarcinoma." (PMID 29285217, 2017).
lung mucinous adenocarcinoma (1 paper, 2023). "Moreover, HNF-4α is reported as part of the signature genes of invasive lung mucinous adenocarcinoma, together with FOXA3, SPDEF and mucins, such as MUC5AC, MUC5B, and MUC3." (PMID 36674438, 2023).
lymph node metastasis (1 paper, 2024). "In patients with lymph node metastasis of CRC, ETV4 expression was significantly upregulated, whereas SPDEF and SPIB expression was significantly downregulated." (PMID 38200280, 2024).
neuroendocrine carcinoma (1 paper, 2023). A malignant neuroendocrine neoplasm composed of cells containing secretory granules that stain positive for NSE and chromogranin. "Promoter methylation of SAM pointed domain containing ETS transcription factor (SPDEF), which encodes prostate-derived ETS factor (PDEF) and functions as a transcription activator and cell differentiation regulator, was observed in neuroendocrine cancer cell line NCI-H660." (PMID 37240468, 2023).
non-small cell lung carcinoma (1 paper, 2025). A group of at least three distinct histological types of lung cancer, including non-small cell squamous cell carcinoma, adenocarcinoma, and large cell carcinoma. "Moreover, in non-small-cell lung cancer samples, SPDEF was shown to deplete the expression of WDR11-DT, a radiosensitizing long non-coding RNA that suppresses base excision and homologous recombination DNA repair mechanisms." (PMID 40723262, 2025).
otitis media (1 paper, 2012). Inflammation of the anatomical structures of the middle ear, which is most often caused by an infectious process. "Atoh1 and SPDEF could be the therapeutic targets for otitis media associated with mucous cell metaplasia which is frequently considered “intractable” in the clinical settings." (PMID 22518155, 2012). "The effective blockage of the Atoh1, SPDEF, or GFI1 expression in the early phase of disease may be a new strategy for treating intractable otitis media." (PMID 22518155, 2012).
papilloma (1 paper, 2017). A benign epithelial neoplasm that projects above the surrounding epithelial surface and consists of villous or arborescent outgrowths of fibrovascular stroma. "Although both transgenic mouse models developed mucinous lung tumors, induction of SPDEF along with KRASG12D produced malignant mucinous lung tumors (tubulopapillary‐like carcinoma), while induction of FOXA3 along with KRASG12D produced benign mucinous lung tumors (e.g., papilloma)." (PMID 28255028, 2017).
pulmonary fibrosis (1 paper, 2024). Chronic progressive interstitial lung disorder characterized by the replacement of the lung tissue by connective tissue, leading to progressive dyspnea, respiratory failure, or right heart failure. "Previous studies have shown that SPDEF expression is reduced in animal models of pulmonary fibrosis." (PMID 39736520, 2024).
renal fibrosis (1 paper, 2024). A final common manifestation of a wide variety of chronic kidney diseases characterized by glomerulosclerosis and tubulointerstitial fibrosis. "To further demonstrate the role of SPDEF in renal fibrosis, we construct an SPDEF knockdown UUO mice model by injecting a virus into the renal cortex." (PMID 39736520, 2024). "To further demonstrate the role of SPDEF in renal fibrosis, we determined the role of SPDEF in a cell model of renal fibrosis that was induced by TGF-β1." (PMID 39736520, 2024). "Additionally, we found that overexpression of SPDEF can improve UUO-induced renal fibrosis in mice and TGF-β1-induced fibrosis in HK-2 by transcriptionally activating NR4A1." (PMID 39736520, 2024). "Additionally, we found that knocking down SPDEF could aggravate UUO-induced or TGF-β1-induced renal fibrosis." (PMID 39736520, 2024). "We hypothesized that SPDEF could inhibit renal fibrosis by activating NR4A1." (PMID 39736520, 2024). "Therefore, we first detected the expression of SPDEF in renal fibrosis." (PMID 39736520, 2024). "Therefore, we speculate that SPDEF can inhibit renal fibrosis by transcriptionally activating NR4A1." (PMID 39736520, 2024). "We studied the role of SPDEF and NR4A1 in renal fibrosis and their interaction by knocking down either of them." (PMID 39736520, 2024). "SPDEF is a transcription factor that can activate NR4A1 transcriptionally and subsequently contribute positively in the regulation of renal fibrosis." (PMID 39736520, 2024). "Our results have demonstrated that both SPDEF and NR4A1 can negatively regulate the development of renal fibrosis." (PMID 39736520, 2024). "Previous research has shown that the SAM pointed domain containing Ets transformation-specific transcription factor (SPDEF) can activate NR4A1, but its mechanism of action in renal fibrosis is not yet clear." (PMID 39736520, 2024).
Sjögren's syndrome (1 paper, 2021). "In our investigation on ocular surface mucin alterations in Sjögren's syndrome, we reported that SPDEF and MUC16 mRNA expression levels are suitable markers for ocular surface mucin in the patients with Sjögren's syndrome." (PMID 34194821, 2021).
triple-negative breast carcinoma (1 paper, 2022). An invasive breast carcinoma which is negative for expression of estrogen receptor (ER), progesterone receptor (PR), and human epidermal growth factor receptor 2 (HER2). "SPDEF is a tumor suppressor in triple-negative breast cancer (TNBC) inhibiting tumor invasion and decreasing epithelial–mesenchymal transformation (EMT)." (PMID 35906698, 2022).
tumor (61 papers, 2007 to 2025). "In luminal cells, loss of SPDEF has been associated with decreased luminal differentiation and subsequently increased tumor survival and endocrine therapy resistance." (PMID 41228349, 2025). "These associations suggest that SPDEF silencing disproportionately affects clinically aggressive tumor subtypes and certain demographic groups." (PMID 41228349, 2025). "Meanwhile, in Basal cells, loss of SPDEF has been associated with increased tumor survival and invasiveness." (PMID 41228349, 2025). "Conversely, SPDEF expression is up-regulated during BC progression, associated with increased tumor aggressiveness, suggesting instead a possible oncogenic role." (PMID 37633945, 2023). "SPDEF is markedly upregulated in luminal BC and positively associated with tumor progression and poor prognosis." (PMID 37633945, 2023). "But remarkably, high SPDEF expression was positively associated with stage (P = 0.022) and tumor invasion (P = 0.031)." (PMID 37633945, 2023). "Few studies focus on the mechanisms underlying the pro-oncogenic or tumor suppressive activity of SPDEF depending on different BC subtypes." (PMID 37633945, 2023). "In TNBC, a tumour suppressive role is suggested by the loss of SPDEF protein in TNBC cell lines, which has been linked to inhibition of translation of SPDEF mRNA by miR-204 and miR-510." (PMID 30200227, 2018). "Decreased prostate carcinogenesis in SPDEF-deficient mice was associated with decreased proliferation of tumor cells and reduced expression of Cdc25b, Cyclin B1, Plk-1, AuroraB, and Topo2alpha, factors that are critical for tumor cell proliferation." (PMID 25254494, 2014). "Since the role of SPDEF in PCa remains controversial, we generated transgenic mice with loss- and gain-of-function of SPDEF to demonstrate that SPDEF functions as a tumor suppressor in PCa." (PMID 25254494, 2014). "Loss of SPDEF increased cancer progression and tumor cell proliferation, whereas over-expression of SPDEF in prostate epithelium inhibited carcinogenesis and reduced tumor cell proliferation in vivo and in vitro." (PMID 25254494, 2014). "However, a survey of more than 9,000 prostate tumor samples shows that expression of SPDEF is detected in 80% of these samples and its positivity is associated with the Gleason grade tumor stage and poor prognosis." (PMID 37305018, 2022). "Notably, in Luminal A, high SPDEF expression was positively associated with TNM stage (P = .004), lymphoid nodal status (P = .023), whereas in Luminal B, high SPDEF expression was positively associated with tumour invasion (P = .025)." (PMID 34191390, 2021). "The results showed that lower SPDEF protein levels were associated with more advanced tumor phenotypes, including primary tumor size (P = 0.034), regional lymph node metastasis (P = 0.019), and tumor node metastasis (TNM) stage (P = 0.019)." (PMID 34667150, 2021). "Interestingly, re-expression of Foxm1 in SPDEF-deficient tumor cells restored cell migration, coinciding with elevated levels of MMP2, MMP9 and MMP13." (PMID 25254494, 2014). "However, the loss of SPDEF during tumor progression was reported by other groups." (PMID 25254494, 2014). "Future studies involving larger and more diverse populations are warranted to validate these results and to explore the mechanistic role of SPDEF in tumor progression and immune modulation." (PMID 40457266, 2025). "Methylation levels at the CpG dinucleotide cg11346722, located within the SPDEF gene region (Chr6:34544344–34544482), were significantly lower in tumor samples compared to normal prostate tissues (Wilcoxon p = 6.2 × 10−13)." (PMID 40457266, 2025). "Given its role in restricting cellular plasticity and promoting a luminal epithelial phenotype, SPDEF is considered critical in tumor growth and metastasis." (PMID 40457266, 2025).
tumor (continued). "Our results are consistent with previous studies reporting tumor-suppressive properties of SPDEF in cancers of the prostate, colon, and head and neck, where its loss was found to contribute to more aggressive disease phenotypes." (PMID 41228349, 2025). "ACSL5 was found to function as an immune-dependent tumor suppressor, and SPDEF and FOXA1 are the canonical markers of mammalian “goblet cells”." (PMID 40429746, 2025). "Elevated SPDEF expression was observed in PAAD tumor samples, further establishing its role in this disease." (PMID 38520747, 2024). "In contrast, the overexpression of SPDEF leads to a reduction in mRNA and protein levels of TF Foxm1, leading to tumor proliferation." (PMID 38674385, 2024). "Analysis of SPDEF expression across PAAD tumor stages identified elevated SPDEF levels in stage 2 tumors." (PMID 38520747, 2024). "Further examination revealed a notable increase in SPDEF levels in PAAD tumor samples, suggesting its oncogenic function." (PMID 38520747, 2024). "Genetic knockdown of SPDEF using siRNA efficiently reduced OPA1 expressions in tumor spheres, supporting SPDEF-instructed high OPA1 in CSCs." (PMID 36809297, 2023). "Meanwhile, the growth rate of tumor volume and the average weight of harvested nodules were also inhibited in SPDEF knockdown tumors compared to control group." (PMID 37633945, 2023). "Accordingly, the genetic knockdown of SPDEF persistently impaired the sphere formation ability of tumor spheres." (PMID 36809297, 2023). "In NSCLC tumor spheres, SPDEF binds to the OPA1 gene, promoting OPA1 expression, mitochondrial fusion activity, and stem-like properties." (PMID 36809297, 2023). "Cluster 4 was predicted to be a goblet cell-like cluster because it was enriched with tumor suppressors and developmental transcription factors for intestinal cells, such as SPDEF or POU2F3, and goblet cell markers." (PMID 38084922, 2023). "Several studies have demonstrated that SPDEF expression is lost in invasive BC cancer cell lines, supporting a tumor-suppressive function." (PMID 37633945, 2023). "More studies is needed to elucidate the detailed role of SPDEF in the tumor progression and EMT in prostate cancer." (PMID 37305018, 2022). "Here, we demonstrate that SPDEF acts as a tumor suppressor by transcriptionally activating NR4A1 in HNSCC." (PMID 34667150, 2021). "SPDEF exerted its tumor suppressive effects by directly regulating the NR4A1/oncogenic signaling axis in HNSCC." (PMID 34667150, 2021). "SAM pointed domain containing ETS transcription factor (SPEDF) is a tumor suppressor involved in tumor progression via p21/CIP1 regulation." (PMID 33883026, 2021). "Given that the NF-κB signaling pathway plays critical roles in immune response regulation and tumor cell formation, we explored alterations in genes in the NF-κB signaling pathway in SPDEF-overexpressing cells." (PMID 34667150, 2021). "CCK8, colony formation, cell cycle analysis, and a xenograft tumor growth model were used to determine the molecular functions of SPDEF in HNSCC." (PMID 34667150, 2021). "The xenograft tumor growth model showed that tumors with SPDEF overexpression had slower growth rates, smaller volumes, and lower weights." (PMID 34667150, 2021). "These bioinformatics and clinical findings have added a new dimension to our knowledge about SPDEF in addition to its role only as an oncogene or a tumour suppressor in BC." (PMID 34191390, 2021). "Nonetheless, they observed elevated expression of KDM4B, XBP1, AR, MYB, and SPDEF in early neoplasias compared to normal which were also elevated in our profile." (PMID 31248446, 2019). "SPDEF mRNA and protein expression is reduced in HCC, particularly in poorly differentiated tumours, and is associated with worse patient outcome." (PMID 30200227, 2018).
tumor (continued). "Supporting a tumour suppressive role, SPDEF re-expression in SPDEF-negative OC cells inhibited cell proliferation and induced apoptosis, which was associated with reduced expression and promoter activity of the pro-survival gene, survivin (BIRC5)." (PMID 30200227, 2018). "Within these, 13 were altered in the same direction (5 up and 8 down in the tumor compared with normal), while SPDEF was oppositely regulated in basal compared with other subtypes." (PMID 26738740, 2016). "Emerging functional evidence implies that GADD45 proteins serve as tumor suppressors in response to diverse stimuli and our results support this notion as GADD45α inhibited SPDEF degradation and thereby reduced migration and invasion." (PMID 26885618, 2016). "Expression of SPDEF in TRAMP mice was sufficient to inhibit prostate carcinogenesis as demonstrated by decreased tumor weight in TRAMP/SPDEF OE mice when compared to TRAMP mice." (PMID 25254494, 2014). "Proliferation defects in SPDEF-containing tumor cells were corrected by re-expression of Foxm1, providing direct evidence that SPDEF inhibits tumor cell proliferation through Foxm1." (PMID 25254494, 2014). "Inverse correlation between Foxm1 and SPDEF expression levels was also found when metastatic and primary tumor samples were compared." (PMID 25254494, 2014). "While some studies examined SPDEF expression in tumor samples classified by Gleason scores, others used pooled tumor samples." (PMID 25254494, 2014). "Whereas some studies propose a putative role for SPDEF as a tumor suppressor, others suggest a prometastatic function." (PMID 20862312, 2010). "Additionally, functional validation of SPDEF’s tumor-suppressive role was beyond the scope of this study." (PMID 41228349, 2025). "It has been revealed that SPDEF has both oncogenic and tumor-suppressive properties." (PMID 40457266, 2025). "In contrast, goblet cell markers, such as KLF4, mucin 2 (MUC2), and SAM pointed domain-containing Ets transcription factor (SPDEF), were consistently downregulated in tumor tissue, aligning with the literature describing a reduced goblet cell population in the neoplastic intestinal epithelium." (PMID 41303610, 2025). "We show that SSEA‐1+ EECs play a role in endometrial tissue homeostasis and tumor suppression, and bioinformatically identify potential upstream regulators such as SPDEF and TGFB1, which may be involved in these mechanisms." (PMID 40297954, 2025). "However, in other reports, SPDEF has been identified as a tumor suppressor, especially in metastatic PCa cases." (PMID 38674385, 2024). "SPDEF expression in tumor tissue is organ- as well as subtype-specific." (PMID 38674385, 2024). "SPDEF is localized to chromosome 6p21.31, encodes a 335 aa protein, preferentially binds the target gene through the high-affinity sequence of GGAT, and is frequently reported to play a suppressive function in tumor progression and metastasis." (PMID 36809297, 2023). "In line with the high OPA1 in CSCs, SPDEF was expressed at a higher level in tumor spheres." (PMID 36809297, 2023). "However, the precise functions of SPDEF in different cancers and tumor cell subsets still deserve successive studies." (PMID 36809297, 2023). "SPDEF also is with both oncogenic and tumor-suppressor functions in BC." (PMID 37715225, 2023). "The analysis of a cohort of 195 men showed that the expression of PCA3 and ERG genes (including the fusion gene TMPRSS2:ERG) normalised to the level of SPDEF (SAM-pointed domain-containing Ets transcription factor) can be used to differentiate between GS ≤ 6 and GS ≥ 7 tumours." (PMID 34811504, 2022). "In addition, SPDEF can drive luminal differentiation of basal mammary epithelial cells, regulate the survival of luminal tumor cells, and contribute to endocrine resistance." (PMID 28915724, 2017). "SPDEF acts as a tumor suppressor in colorectal cancer through the E-cadherin and β-catenin pathway and may play similar roles in a number of other epithelial cancers." (PMID 26885618, 2016).